PIK3CA (phosphatidylinositol-4,5-bisphosphate 3-kinase catalytic subunit alpha)
Diseases named in the same sentence as PIK3CA in open-access papers (continued):
Sharing a sentence is not in itself a finding about the gene and the disease.
Wilms tumor (4 papers, 2017 to 2024). An embryonal neoplasm characterized by the presence of epithelial, mesenchymal, and blastema components. "No pathogenic PIK3CA mutations and three pathogenic ARID1A mutations (two of which were germline) were identified in a whole genome sequencing study of 117 cases of Wilms’ tumor." (PMID 32490123, 2020). "A further five constitutionally mutated genes—PIK3CA, FBXW7, ASXL1, BRCA2, and CDC73—were somatically mutated in other cancer types but have not been proven to be somatic drivers in Wilms tumour." (PMID 30885698, 2019).
adenosquamous carcinoma (3 papers, 2014 to 2025). A carcinoma composed of malignant glandular cells and malignant squamous cells. "Transgenic mice that carry the PIK3CA-H1047R mutation in the Rosa 26 locus express the PI3Ka mutation in mammary epithelial cells when CRE expression is under the control of the MMTV promoter and develop adenosquamous carcinoma or adenomyoepithelioma." (PMID 25295225, 2014).
apocrine carcinomas (3 papers, 2010 to 2025). "PIK3CA mutations and PTEN protein expression (IHC) were analyzed in luminal tumors (ER and/or PgR positive), molecular apocrine carcinomas (MAC; ER/PgR negative / AR positive) and hormone receptor (ER/PgR/AR) negative tumors." (PMID 26452060, 2015).
arteriovenous malformations (3 papers, 2022 to 2023). "Here, we identified a putative new tumor type characterized by the same dural location, a similar histopathological pattern and a frequent GJA4 p.Gly41Cys mutation (3/6 cases), distinct from genes implicated in CCM (CCM1/2/3, MAP3K3, PIK3CA) and arteriovenous malformations (KRAS) of the brain." (PMID 35642047, 2022). "Unlike patients with PIK3CA or RASopathy postzygotic mutations, our patients with WILD syndrome do not have segmental overgrowth or arteriovenous malformation." (PMID 34916230, 2023).
Arthritis (3 papers, 2019 to 2023). Inflammation of a joint. "Thus, to analyze the role of p110α PI3-kinase in T-cell function in an experimental model of induced arthritis, mice with conditional deletion of the pik3ca gene in T cells were generated as we have previously reported." (PMID 34203838, 2021). "The present study predicted that PIK3CA and AKT are the most common genes found in the top pathways of phytocannabinoids to combat arthritis." (PMID 36983855, 2023).
bone metastasis (3 papers, 2012 to 2026). Transfer of a neoplasm from its primary site to bones. "In the NGS subset (5 PIK3CA-mutant), PIK3CA mutation (OS HR 6.19, p = 0.024) and bone metastasis (OS HR 5.84, p = 0.027) remained associated with shorter OS after adjustment." (PMID 42279429, 2026). "For the four cases, the PIK3CA mutation status was the same between the primary and the bone metastasis sample." (PMID 22970388, 2012). "Moreover, patients harbored PIK3CA H1047X mutation were significantly associated with bone metastasis (61.2 vs. 40.6%, P = 0.004, adj P = 0.0025)." (PMID 32695676, 2020).
bowel cancer (3 papers, 2018 to 2024). "The coexistence of APC alterations with PIK3CA mutation may be partially explained by a previous study using a mouse model with PIK3CA mutation, which demonstrated that the PIK3CA mutation alone was insufficient to initiate intestinal tumorigenesis in intestinal cancers." (PMID 30115035, 2018).
colorectal polyps (3 papers, 2008 to 2017). "We aimed at determine the frequency of KRAS, BRAF and PIK3CA mutations in the process of colorectal tumourigenesis using a series of colorectal polyps and carcinomas." (PMID 18782444, 2008). "In contrast to CRC, the data of PIK3CA mutations in colorectal polyps remained few." (PMID 25551625, 2014). "Mutations in KRAS, PIK3CA or BRAF occur in 12 (70.6%) of the 17 colorectal polyps." (PMID 18782444, 2008). "In our series of colorectal polyps we found the majority (71%) harbour mutations in KRAS (35.3%), PIK3CA (5.9%) or BRAF (29.4%) genes." (PMID 18782444, 2008). "In our series of colorectal polyps, we found that mutations in KRAS, PIK3CA or BRAF are mutually exclusive and occur in the majority of these pre-malignant colorectal lesions." (PMID 18782444, 2008).
developmental delay (3 papers, 2019 to 2025). "Herein, we describe a patient with macrocephaly and mild developmental delay in whom the c.1090G>C (p.Gly364Arg) pathogenic variant in PIK3CA was detected in different tissues in a non‐mosaic status." (PMID 31290289, 2019).
dysplasia (3 papers, 2015 to 2020). A usually neoplastic transformation of the cell, associated with altered architectural tissue patterns. "We used primary human tracheobronchial basal cells to investigate how copy number gains in SOX2 and PIK3CA at 3q26-28, which co-occur in dysplasia and are observed in 94% of SQCCs, may promote progression." (PMID 27880766, 2016).
embryonal rhabdomyosarcoma (3 papers, 2016 to 2022). A poorly circumscribed morphologic variant of rhabdomyosarcoma. "The second patient was a 28-year-old female with PIK3CA-mutated metastatic embryonal rhabdomyosarcoma, who was treated with everolimus after progression on vincristine, dactinomycin, and cyclophosphamide." (PMID 36430703, 2022). "Recurrent mutations in the myogenic transcription factor MYOD1 and PIK3CA were initially described in a subset of embryonal rhabdomyosarcomas." (PMID 27562493, 2016). "The two main subtypes are alveolar rhabdomyosarcoma (ARMS), which is associated with PAX3/7-FOXO1 fusion genes, and embryonal rhabdomyosarcoma (ERMS), which is associated with mutations in common cancer genes such as HRAS, KRAS, NRAS, CTNNB1, PIK3CA and TP531." (PMID 30353028, 2018).
endometrioid endometrial carcinoma (3 papers, 2010 to 2023). "Three patients with mutations in all three PI3K pathway genes had grade 2 endometrioid endometrial carcinoma, while the patient with only PIK3CA and PTEN mutations was diagnosed with grade 1 endometrial cancer." (PMID 36765826, 2023). "PIK3CA mutations, particularly exon 20 mutations or PIK3CA mRNA overexpression, are frequent in endometrioid endometrial carcinoma in association with invasion and adverse prognostic factors such as blood vessel invasion." (PMID 20368795, 2010). "Concerning endometrial endometrioid carcinoma, cases presenting genes with alterations in PTEN (71%), PIK3CA (60%), and NOTCH1 (43%) were the most observed." (PMID 36010253, 2022). "Furthermore, none of the five main alterations of endometrioid endometrial carcinoma (mutations of PTEN, PIK3CA, KRAS, and CTNNB1 genes and MSI) plays a major role in non-endometrioid endometrial carcinoma." (PMID 20368795, 2010).
gastrointestinal stromal tumor (3 papers, 2015 to 2021). "Patients treated with imatinib for gastrointestinal stromal tumor (GIST) with c-KIT mutations in exon 11 have an 83.5% response rate versus 47.8% in patients with exon 9 mutations, and PIK3CA H1047R mutations may be more sensitive to PI3K/Akt/mTor inhibitors than other PIK3CA mutations." (PMID 26418953, 2015).
germ cell tumor (3 papers, 2020 to 2025). A benign or malignant, gonadal or extragonadal neoplasm that originates from germ cells. "PIK3CA and AKT1 mutations have been identified in cisplatin-resistant germ cell tumors, and phospho-AKT levels are significantly higher in cisplatin-resistant TGCTs compared with cisplatin-sensitive ones." (PMID 33212946, 2020).
hemorrhage (3 papers, 2022 to 2025). Loss of blood from the vascular compartment to the exterior or into nonvascular body space as a result of rupture or severance of the blood vessels. "In addition, multivariate Cox regression analysis revealed that a PIK3CA mutation (hazard ratio: 2.96 [95% confidence interval: 1.03–8.49]; p = 0.044) was a significant risk factor for early hemorrhage after diagnosis." (PMID 40478424, 2025). "We examined the association between PIK3CA and MAP3K3 mutations and hemorrhage during the follow-up after CM diagnosis." (PMID 40478424, 2025). "A recent study showed that patients with PIK3CA mutations had a higher rate of hemorrhage as the initial symptom of CCM diagnosis than those with only the MAP3K3 I441M mutation and those with both the PIK3CA mutation and the MAP3K3 I441M." (PMID 40478424, 2025). "CDKN2B, KMT5B, and PIK3CA alterations were common in the hemorrhage group, suggesting a possible mechanism for the prognostic value of intratumoral hemorrhage." (PMID 38877400, 2024). "Molecular analysis indicated that CDKN2B, KMT5B, and PIK3CA alteration occurred more in the hemorrhage group (CDKN2B, 84.4% vs. 62.2%, p = 0.029; KMT5B, 25.0% vs. 8.9%, p = 0.029; and PIK3CA, 81.3% vs. 58.5%, p = 0.029)." (PMID 38877400, 2024).
Intellectual disability (3 papers, 2016 to 2022). "We noted a somatic variant in PIK3CA based on clinical suspicion in an undiagnosed patient with hemihypertrophy, macrocephaly, and intellectual disability." (PMID 36209187, 2022). "Germline variants in PIK3CA are associated to a mild phenotype characterized by overgrowth, severe macrocephaly, mild intellectual disability, and few dysmorphic features." (PMID 31290289, 2019). "Finally, we report on constitutional mutations of PIK3CA in a subset of children, some of whom have milder features such as diffuse megalencephaly with intellectual disability, similar to the PTEN-related disorders." (PMID 27631024, 2016).
intrahepatic cholangiocarcinoma (3 papers, 2021 to 2024). A carcinoma that arises from the intrahepatic bile duct epithelium in any site of the intrahepatic biliary tree.
malignant phyllodes tumor (3 papers, 2022 to 2025). A phyllodes tumor with sarcomatous stroma. "Two additional patients with malignant phyllodes tumours had pathogenic PDGFRB and PIK3CA mutations, respectively)." (PMID 40144205, 2025). "Both patients with malignant phyllodes tumours and pathogenic PDGFRB and PIK3CA mutations received multi-thyrosine kinase inhibitor therapy but died of the disease." (PMID 40144205, 2025). "One probably damaging (PolyPhen-2) PIK3CA mutation was observed also in TOMAS-39 patient, affected by malignant phyllodes tumor (MPT)." (PMID 36110934, 2022). "PIK3CA/KRAS and HRAS alterations have already been reported in borderline and malignant phyllodes tumors." (PMID 37240386, 2023).
metastatic melanoma (3 papers, 2012 to 2024). A melanoma that has spread from its primary site to another anatomic site. "We have examined the utilisation of these three signalling pathways in a number of cell lines derived from patients with metastatic malignant melanoma of known PIK3CA, PTEN, NRAS and BRAF mutational status." (PMID 22475322, 2012). "Overall, in metastatic melanoma, the PI3K pathway is altered by somatic mutations in a wide array of genes including PIK3CA, MTOR, PIK3R1, PIK3R5, and IRS4." (PMID 22912864, 2012).
mucinous ovarian tumors (3 papers, 2015 to 2024).
myocardial hypertrophy (3 papers, 2014 to 2024). "Thus the downregulation of Pik3ca and subsequent inhibition in the binding of GRK2 to Pik3ca by wogonin has double significance to the therapy of myocardial hypertrophy." (PMID 30150938, 2018). "Therefore, wogonin targets Nedd4l to induce the degradation of Pik3ca, which reverses the over-activation of the PI3K/Akt pathway and consequently relieves the isoprenaline-induced myocardial hypertrophy." (PMID 30150938, 2018).
neuroendocrine carcinoma (3 papers, 2021 to 2024). A malignant neuroendocrine neoplasm composed of cells containing secretory granules that stain positive for NSE and chromogranin. "PIK3CA, WNK2, and KMT2B underwent mutations in both the dMMR-like subtype of NECC (50% – 75%) and in NECE (60% – 80%) specimens, while exhibiting infrequent mutational occurrences in publicly available data pertaining to neuroendocrine carcinomas of the lung or bladder (< 10%)." (PMID 37920164, 2023).
oropharyngeal squamous cell carcinoma (3 papers, 2013 to 2024). "Notably, PIK3CA amplification has been linked to HPV infection in oropharyngeal squamous cell carcinoma." (PMID 26087196, 2015). "In addition to ESCC, another study performed in oropharyngeal squamous cell carcinoma (OPSCC), Beaty BT and associates, revealed that patients with PIK3CA mutations easily experienced recurrence compared with those without mutations in PIK3CA." (PMID 38616230, 2024).
ovarian serous cystadenocarcinoma (3 papers, 2020). A malignant serous cystic epithelial neoplasm arising from the ovary. "Looking at other UNRES examples, we compared DepMap essentiality scores between GSK690693 resistant and sensitive PIK3CA mutant ovarian serous cystadenocarcinoma cell lines." (PMID 33205120, 2020).
Overgrowth (3 papers, 2021 to 2025). Excessive postnatal growth which may comprise increased weight, increased length, and/or increased head circumference. "PI3K is fundamental for normal brain size and function, with mutations in PIK3CA during embryonic development leading to severe overgrowth disorders known as PIK3CA-Related Overgrowth Spectrum (PROS)." (PMID 40386392, 2025).
pancreatic ductal adenocarcinoma (3 papers, 2015 to 2024). An infiltrating adenocarcinoma that arises from the epithelial cells of the pancreas. "A few of these recurrent neoantigens are from known oncogenic drivers, for example, PIK3CA, MAPK1, ERBB2, ERBB3, and also from the KRAS G12D mutation, which we recently identified as a promising recurrent neoantigen-based immunotherapy target in pancreatic ductal adenocarcinoma." (PMID 28670312, 2017).
parathyroid carcinoma (3 papers, 2019 to 2020). "In two recent studies, gain‐of‐function mutations in PIK3CA, a recognized driver oncogene in many human malignancies, have been newly identified in parathyroid carcinoma." (PMID 32537547, 2020). "Thus, tumor tissue from patients with surgically incurable parathyroid cancer can rationally be subjected to DNA sequencing, with patients proving to harbor clonal somatic activating PIK3CA mutations being considered for appropriately targeted treatment, ideally in the setting of a study." (PMID 32537547, 2020). "It is possible that the presence of an activating PIK3CA mutation may confer malignant potential on a parathyroid cell and that the subpopulations of cells harboring PIK3CA mutations may have been capable, if given enough time and additional genetic alterations, of progressing to parathyroid cancer." (PMID 32537547, 2020). "Recently, it has been raised the possibility that treatment with drugs used in other tumors, directed to mutations of PIK3CA or MTOR or amplification of CCND1, can also be used in metastasized parathyroid carcinoma, as these mutations are also frequent in this neoplasia." (PMID 32884778, 2020).
phyllodes tumor (3 papers, 2016 to 2024). A benign, borderline, or malignant fibroepithelial neoplasm arising from the breast and rarely the prostate gland.
RASopathies (3 papers, 2021 to 2023). "We have looked for PIK3CA and related gene mutations in the AKT pathway and the RASopathy genes in DNA from affected skin in two of our patients." (PMID 34916230, 2023).
rectal adenocarcinoma (3 papers, 2020 to 2026). "For prediction of PIK3CA mutation status in rectal adenocarcinoma (READ), we observed the best cross-cancer type performance for relatively low levels of regularization/high x axis values at α=0.027." (PMID 39776849, 2024). "Overall mucinous rectal cancers are more likely to be MSI-H and to have KRAS, BRAF, and PIK3CA mutations when compared to rectal adenocarcinoma NOS." (PMID 32984045, 2020).
round cell liposarcoma (3 papers, 2014 to 2016). A poorly differentiated liposarcoma, characterized by the presence of solid sheets of primitive round mesenchymal cells and the absence of myxoid stroma. "Recently, PIK3CA mutation was reported in 12% and 18% of myxoid/round-cell liposarcoma, and it was associated with Akt activation and poor clinical outcome." (PMID 27016421, 2016). "PIK3CA mutation has been reported 14–18.3% of myxoid/round-cell liposarcoma and associated with shorter DFS with mass spectrometry-based genotyping." (PMID 27016421, 2016). "Previous work has demonstrated PIK3CA mutations in 14–18% of myxoid and round cell liposarcoma." (PMID 25906748, 2015).
salivary gland cancer (3 papers, 2015 to 2025). A primary or metastatic malignant neoplasm that affects the major or minor salivary glands. "Importantly, the PIK3CA in case 6 and NRAS in case 1 and 3 are rational candidates for off-label targeted treatments and the NOTCH1 mutation in case 1 is eligible for inclusion in an ongoing clinical trial for advanced salivary gland cancers (clinicaltrials.gov identifier: NCT020697309)." (PMID 29731974, 2018).
sarcopenia (3 papers, 2022 to 2025). Progressive decline in muscle mass due to aging which results in decreased functional capacity of muscles. "Applying MTA-MO to multi-omics data identified seven potential hub genes associated with sarcopenia: ESR1, ATM, CDC42, EP300, PIK3CA, EGF, and PTK2B." (PMID 41303670, 2025). "Using the MTA‐MO method, we identified 639 gene targets, and by analysing PPIs and querying public databases, we narrowed this list down to seven potential hub genes associated with sarcopenia (ESR1, ATM, CDC42, EP300, PIK3CA, EGF and PTK2B)." (PMID 40045692, 2025). "Then, MC-sarcopenia targets were filtered to obtain four core proteins, namely PIK3CA, AKT1, EGFR, and INS." (PMID 35176999, 2022). "Seven main active components (Anonaine, Eucalyptol, Neohesperidin, Obovatol, Honokiol, Magnolol, and beta-Eudesmol) and 26 target proteins of MC-sarcopenia, of which 4 were core proteins (AKT1, EGFR, INS, and PIK3CA), were identified." (PMID 35176999, 2022). "Furthermore, the results of molecular docking showed that there exists direct hydrogen bondings between the active components (Honokiol, Magnolol, and Obovatol) of MC and the core proteins of sarcopenia (AKT1, EGFR, INS, and PIK3CA), which verifies our analysis and prediction from another angle." (PMID 35176999, 2022).
seminoma (3 papers, 2018 to 2025). A radiosensitive malignant germ cell tumor found in the testis (especially undescended), and extragonadal sites (anterior mediastinum and pineal gland). "Of note, three seminomas contained PIK3CA mutations, two at E545K and one at N345K." (PMID 29898407, 2018). "Association with seminoma was found for mutations in KIT, KRAS and NRAS and for putative oncogenic driver genes CBL, RAC1, PIK3CA, and CTNNB1 (analysed jointly due to lower frequency), p = 3.33 × 10−10, p = 1.41 × 10−6, p = 0.002, p = 0.009, respectively." (PMID 32366847, 2020). "While WGD was typically among the earliest events in TGCTs, a subset of seminomas (N=25, 17.4%) harbored driver mutations in KIT, KRAS, NRAS, or PIK3CA prior to WGD, irrespective of WGD timing." (PMID 40568177, 2025).